ACE (angiotensin I converting enzyme)
Diseases named in the same sentence as ACE in open-access papers (continued):
Sharing a sentence is not in itself a finding about the gene and the disease.
sarcoidosis (continued). "ACE (angiotensin converting enzyme) levels are usually only elevated in sarcoidosis but there was a reported case where a patient had elevated ACE levels and Histoplasma grew from the liver biopsy specimens." (PMID 26345350, 2015). "As a result, the recommended workup to accurately differentiate between sarcoidosis and histoplasmosis should include radiography, tissue biopsies, cultures, ACE level, serology, PCR assay, and urine antigen." (PMID 26345350, 2015). "In patients with sarcoidosis, serum ACE levels are elevated due to marked synthesis by epithelioid cells, thus the ACE level reflects the mass of ACE-producing granuloma cells." (PMID 24555559, 2014). "Both of them had elevated levels of serum ACE, which were compatible with sarcoidosis, but in both elevated levels of immunoglobulin light chains in urine were found, which conducted to the AL amyloidosis suspicion." (PMID 24826302, 2013). "The increased levels of angiotensin converting enzyme (ACE) in some patients with sarcoidosis has led to interest and enthusiasm in evaluation of ACE gene polymorphisms." (PMID 23533794, 2013). "An elevated angiotensin converting enzyme (ACE) level can be found in sarcoidosis patients, however it is a less sensitive test in children than in adults and is thought to be a product of the epithelioid cells of the sarcoid granuloma." (PMID 22937766, 2012). "In healthy individuals, the level of ACE in the blood is very stable, whereas significant increase (2-4-fold) in blood ACE activity was observed in granulomatous diseases such as sarcoidosis and Gaucher’s disease." (PMID 23166630, 2012). "Nevertheless, for this child, the constellation of uveitis, arthritis, pleuritis, and rash in the setting of an elevated ACE level and granulomas on biopsy strongly argue in favor of coincident diagnosis of sarcoidosis." (PMID 22937766, 2012). "Findings in support of a diagnosis of sarcoidosis include a history of skin or ocular lesions, hilar or mediastinal lymphadenopathy, chronic fatigue, and elevated serum levels of angiotensin-converting enzyme (ACE)." (PMID 23146172, 2012). "BAFF levels were also strongly correlated with serum ACE levels in patients with sarcoidosis (r = 0.61; p = 0.00022)." (PMID 22927996, 2012). "* Angiotensin converting enzyme (ACE) is usually up-regulated in macrophage activation in diseases such as sarcoidosis and tuberculosis." (PMID 22410181, 2011). "In healthy individuals, the level of ACE in the blood is very stable, whereas granulomatous diseases (sarcoidosis in particular) and Gaucher's disease lead to a significant increase of ACE activity in the blood." (PMID 20011602, 2009). "Serial serum ACE measurements now are an essential tool for the diagnosis and monitoring the clinical course of sarcoidosis." (PMID 20011602, 2009). "ACE serum levels have been shown to be useful in diagnosing sarcoidosis and following disease activity and the effect of therapy in older children with sarcoidosis." (PMID 18811966, 2008). "Although serum ACE is usually increased in sarcoidosis, the test has low disease specificity and needs to be carefully interpreted in the light of the overall differential diagnosis." (PMID 17335577, 2007). "Although some investigators suggest that a rising ACE serum level can predict radiographic relapses of sarcoidosis others have clearly demonstrated that ACE appears to be of poor prognostic value." (PMID 16042760, 2005). "As for sarcoidosis, despite the controversial aspects regarding the usefulness of ACE in reflecting the disease activity, it still remains the most reliable and well defined marker whereas sIL-2R represents one of the most fruitful applications." (PMID 16042760, 2005). "Therefore, this study aimed to investigate the relationship between FDG-PET/CT metabolic findings and serum ACE and calcium (Ca2+) levels as surrogate indicators of inflammatory metabolic intensity in sarcoidosis." (PMID 41594254, 2026).
sarcoidosis (continued). "While the angiotensin-converting enzyme (ACE) test is more sensitive than specific, it may provide diagnostic clues for sarcoidosis." (PMID 40386698, 2025). "Activated macrophages can produce serum angiotensin-converting enzyme (s-ACE), which could be used as a biomarker for sarcoidosis and believed to reflect granuloma burden." (PMID 39939699, 2025). "Serum and CSF ACE levels may be elevated and can be used as supporting evidence for sarcoidosis, but their sensitivity is limited, though in our patient, significant CSF ACE elevation supported the diagnosis after infectious and malignant causes were excluded." (PMID 41306810, 2025). "One of the prominent features of sarcoidosis is high angiotensin-converting enzyme (ACE) levels." (PMID 39859309, 2025). "ACE and chitotriosidase are biomarkers used for diagnosing sarcoidosis and could have a place in determining the activity of the disease when compared with the results of PET/CT scans." (PMID 40386527, 2025). "Additionally, normal acute-phase reactants, serum calcium, and ACE levels helped exclude inflammatory or granulomatous diseases like sarcoidosis." (PMID 40951256, 2025). "Interestingly, ACE concentration was elevated in this patient, as in 60% of patients with active sarcoidosis." (PMID 40161186, 2025). "Additionally, several researchers have verified that serum ACE activity is elevated in a significant portion of patients with granulomatous diseases such as sarcoidosis and silicosis." (PMID 39545094, 2024). "Also, angiotensin-converting enzyme (ACE) was ordered and found raised at 92 U/L, which is considered a marker of sarcoidosis." (PMID 38978890, 2024). "Many patients with sarcoidosis in fact have normal ACE levels." (PMID 39359743, 2024). "Moreover, within a cohort of 25 sarcoidosis patients, it was noted that ACE levels in bronchoalveolar lavage (BAL) fluid exhibited a more robust correlation with clinical observations compared to ACE levels in serum." (PMID 39896373, 2024). "The role of ACE as a universal biomarker for sarcoidosis should be re-evaluated." (PMID 39768579, 2024). "Consider a Gedankenexperiment (thought experiment/hypothetical situation) in which Goldblatt, who served in World War I, does not publish his 1934 paper and that the first association of ACE and disease is the 1975 observation by Jack Lieberman of elevated ACE serum levels in sarcoidosis patients." (PMID 38763333, 2024). "Furthermore, elevated ACE levels correlated poorly with disease activity and disease severity in sarcoidosis in our cohort." (PMID 39768579, 2024). "Periostin, an extracellular matrix protein, was found to be increased in sarcoidosis patients, and may correlate with ACE and IL-2 serum levels." (PMID 38611622, 2024). "However, elevated ACE levels are also encountered in other medical conditions, and the clinical correlation between ACE levels and disease activity in sarcoidosis is disputable as well." (PMID 39768579, 2024). "Since lymphomas, liver cirrhosis, and interstitial lung disease are critical to differentiate from sarcoidosis, we believe that patients with these conditions should be included in the control group when calculating the specificity of ACE levels for diagnosing sarcoidosis." (PMID 39768579, 2024). "In 2021, a novel ACE fingerprinting approach was introduced, utilizing a panel of mAbs and plasma samples to explore the possibility that elevated ACE levels in patients are due to mutations in the ACE gene rather than being related to sarcoidosis." (PMID 38611622, 2024). "Elevated angiotensin-converting enzyme (ACE) levels are seen in 75% of patients with sarcoidosis." (PMID 39135824, 2024). "Our findings showed that only triggering receptors expressed on myeloid cells 2–positive (TREM2-positive) macrophages (TREM2 macrophages) expressing angiotensin-converting enzyme (ACE) and lysozyme, diagnostic markers of sarcoidosis, were found to be increased in cutaneous sarcoidosis granulomas." (PMID 38038136, 2023).
sarcoidosis (continued). "ACE, studied in sarcoidosis since 1975, is the best-known serum biomarker in this disease." (PMID 37721575, 2023). "The expression of ACE by granulomas in sarcoidosis has been hypothesized to link COVID‐19 infection and the emergence of sarcoidosis in previously healthy cases." (PMID 37180324, 2023). "We observed that the percentages of triggering receptor expressed on myeloid cells 2–positive (TREM2-positive) macrophages expressing angiotensin-converting enzyme (ACE) and lysozyme, diagnostic makers of sarcoidosis, were increased in cutaneous sarcoidosis granulomas." (PMID 38038136, 2023). "The most commonly used serum biomarker in sarcoidosis is ACE, with high specificity." (PMID 37868968, 2023). "High ACE levels have been reported in 56%-61% of sarcoidosis patients." (PMID 37090303, 2023). "Therefore, the detection of ACE protein activity is more suitable for the diagnosis and prognosis of sarcoidosis than the detection of ACE activity." (PMID 37868968, 2023). "Similarly, the D allele polymorphism in the angiotensin-converting enzyme gene (ACE), and NOD2, which induces constitutive activation of the transcription factor NF-kB, are associated with early-onset sarcoidosis." (PMID 38390497, 2023). "ACE gene I/D polymorphism is not the main genetic cause of sarcoidosis, although ACE is related to its pathogenesis and more likely changes its progression." (PMID 37868968, 2023). "Sensitivity and specificity of serum ACE in different types of sarcoidosis." (PMID 37868968, 2023). "Case 1: a 51-year old never smoker man had a history of occupational exposure, episodes of acute exacerbations and positive serum precipitins to Penicillium spp suggestive of HP, while the positivity of serum angiotensin converting enzyme (ACE) favored sarcoidosis." (PMID 37925443, 2023). "Therefore, understanding the change of serum ACE levels will help us to carry out immunosuppressive therapy earlier before the diagnosis of sarcoidosis, which is very likely to further improve the survival rate of patients." (PMID 37868968, 2023). "The proportions of APCs expressing ACE (a previously established diagnostic marker for sarcoidosis) and FBP1 (a newly discovered marker in this study) in skin lesions were analyzed in granulomatous skin diseases other than sarcoidosis." (PMID 38038136, 2023). "Intriguingly, ACE expression had been observed in human Mtb and sarcoidosis granulomas, suggesting that ACE+ MΦs may be commonly involved in granulomatous response across different persistent intracellular bacterial infections and pathophysiologic settings." (PMID 36608122, 2023). "For example, ACE inhibitors decrease serum ACE activity, a test used in sarcoidosis diagnosis." (PMID 36817852, 2023). "ACE is one of the first biomarkers used in diagnosing sarcoidosis." (PMID 37510860, 2023). "Therefore, re-evaluating the ACE level in sarcoidosis enhances the understanding of sarcoidosis in clinic." (PMID 37868968, 2023). "The change in the serum ACE level after corticosteroid treatment of sarcoidosis has been reported, but whether the topical application of corticosteroids can also change the level of serum ACE is yet to be studied." (PMID 37868968, 2023). "Only 2 patients had elevated ACE levels, representing 66.6% of those with sarcoidosis." (PMID 35440697, 2023). "Angiotensin-1 converting enzyme (ACE) level was elevated to 111 U/L (normal range 14-82 U/L), and 1,25-vitamin D was elevated to 110 pg/mL (normal range 19.9-79.3 pg/mL), consistent with the diagnosis of sarcoidosis." (PMID 35747109, 2022). "Absence of pulmonary symptoms, normal ophthalmologic examination, normal serum angiotensin-converting enzyme (ACE), lysozyme, and 25 (OH) vitamin D levels, as well as histopathologic examination substantiated the exclusion of sarcoidosis as a prima facie diagnosis in our patient." (PMID 35382864, 2022).
sarcoidosis (continued). "ACE and lysozyme have been traditionally used as diagnostic markers for sarcoidosis, but their sensitivities are not satisfactory, ranging from 29% to 63% for ACE and from 26% to 79% for lysozyme." (PMID 35663496, 2022). "The same author did not identify similarities in ACE levels, but this does not have diagnostic specificity in sarcoidosis either." (PMID 36421591, 2022). "Therefore, elevated serum levels of ACE are more likely to reflect extrapulmonary sarcoidosis involvement." (PMID 35996109, 2022). "Normal serum/CSF ACE level cannot exclude the diagnosis of sarcoidosis." (PMID 35669693, 2022). "While the role of these potential ACE sources in the circulating ACE levels is unknown, it is well established that circulating ACE level increases in sarcoidosis." (PMID 34359878, 2021). "While elevated ACE, sIL-2R and uveitis suggested sarcoidosis, marked necrosis of epithelioid cell granuloma and IgA antibody for MAC strongly indicated MAC infection, especially disseminated MAC according to swelling of the mediastinal and hilar lymphadenopathy and hepatosplenomegaly." (PMID 33865452, 2021). "To date, neither ACE nor sIL2R measurement are recommended as routine tests in the diagnostic work-up, initial assessment or follow up of patients with sarcoidosis." (PMID 34573900, 2021). "It was recently shown that active sarcoidosis could be differentiated from the inactive one through an algorithm involving the association of plasma CHIT1 activity, ACE levels, and high-sensitivity C-reactive protein (hs-CRP) levels." (PMID 34830565, 2021). "The proportion of elevated serum ACE versus lysozyme was compared in the sarcoidosis patients." (PMID 33805490, 2021). "As constitutional complaints in sarcoidosis patients are supposed to derive from inflammation, we tested whether serological parameters of sarcoidosis activity (soluble interleukin-2 receptor, ACE and neopterin) correlate with GHS." (PMID 34861850, 2021). "The active sarcoidosis group (before therapy) was compared to patients in remission/under treatment (indicated as “after therapy”) to address whether CHIT1 versus ACE could discriminate between the different phases of the disease." (PMID 34830565, 2021). "In addition, sIL2R is more sensitive than serum ACE and lysozyme levels for a diagnosis of sarcoidosis, although sIL-2R levels can also be elevated in hematologic malignancy, autoimmune disorders and idiopathic pulmonary fibrosis." (PMID 34573900, 2021). "What has to be kept in mind is the use of ACE inhibitors in patients with sarcoidosis." (PMID 32760396, 2020). "It showed higher sensitivity and specificity than other biomarkers, including angiotensin converting enzyme (ACE), lysozyme and soluble IL-2 receptor and it has been found increased in active sarcoidosis patients showing to predict clinical course, steroid responsiveness and relapse of the disease." (PMID 31906975, 2020). "On the basis of an established cut-off value, the sensitivity and specificity of serum sIL-2R for the detection of sarcoidosis were 88% and 85%, by far superior to angiotensin-converting enzyme (ACE; the classical biomarker for sarcoidosis with a sensitivity of 62% and specificity of 88%)." (PMID 33061828, 2020). "In this cohort, after diagnostic workup and after a definitive diagnosis (sarcoidosis or another disease) was established, we calculated the sensitivity and specificity of sIL-2R in the diagnosis of sarcoidosis and defined the optimal cut-off value and compared this to serum ACE levels." (PMID 31622413, 2019). "ACE and sIL-2R are useful for evaluating sarcoidosis activity." (PMID 31515495, 2019). "Similarly, we found that CD69 expression on MAIT cells was much higher in sarcoidosis patients than in healthy controls and was significantly correlated with the clinical biomarkers ACE and sIL-2R." (PMID 31515495, 2019).
sarcoidosis (continued). "All patients had raised ACE levels and endobronchial ultrasound-guided biopsy was performed on all patients to rule out new metastatic lesions and confirmed the histological diagnosis of sarcoidosis." (PMID 30190931, 2018). "It is possible that, in patients with sarcoidosis, higher serum ACE level could indicate higher disease activity and increased vulnerability for ocular manifestations." (PMID 29785303, 2018). "Also, hs-CRP (p < 0.001), YKL-40 (p < 0.01), sIL-2R (p < 0.001) and ACE (p < 0.001) levels were elevated in active sarcoidosis patients compared to inactive patients." (PMID 30154391, 2018). "Serum ACE was also higher in patients with diffuse splenic involvement in sarcoidosis." (PMID 30154391, 2018). "Although commonly requested, serum ACE has a poor predictive value in sarcoidosis." (PMID 29610651, 2017). "Significant elevation of serum ACE activity has been observed only for patients with sarcoidosis." (PMID 26879979, 2016). "Intraocular inflammation compatible with sarcoidosis associated with elevated serum ACE levels is considered suggestive for diagnosis of presumptive sarcoidosis in patients without having a tissue biopsy." (PMID 26879979, 2016). "The mean (SD) values of serum ACE for patients with AS, BD, presumed sarcoidosis, presumed latent TB, presumed latent syphilis and control group were 29.363 (2.012), 31.227 (15.225), 58.164 (35.110), 33.061 (15.065), 30.527 (16.016) and 20.704 (7.962) U/L respectively." (PMID 26879979, 2016). "Elevated serum ACE levels are significant for patients with presumed sarcoidosis compared to ocular involvement of other autoimmune diseases such as BD and AS, and ocular involvement of infectious diseases such as presumed latent TB and presumed latent syphilis." (PMID 26879979, 2016). "BALF lymphocytes and ACE expression are both important in clinical assessments of sarcoidosis." (PMID 27203210, 2016). "The mean (SD) differences of serum ACE levels between the patients with presumed sarcoidosis and AS, BD, presumed latent TB, presumed latent syphilis and control group were 28.907 (3.735), 26.784 (3.770), 25.776 (3.898), 27.821 (6.155), and 37.016 (4.918) U/L respectively." (PMID 26879979, 2016). "This study compares for the first time the serum ACE and lysozyme levels of patients diagnosed with ocular involvement of autoimmune diseases such as AS, BD and presumed sarcoidosis and ocular involvement of infectious diseases such as presumed latent TB and presumed latent syphilis." (PMID 26879979, 2016). "ACE levels are considered to indicate active disease in patients with sarcoidosis." (PMID 27203210, 2016). "Screening tests that may suggest the presence of sarcoidosis and support the pursuit of a tissue biopsy include elevated Angiotensin Converting Enzyme (ACE) levels, mild hypercalcemia, and hypergammaglobulinemia." (PMID 26136783, 2015). "Serum levels of some biochemical indicators, such as angiotensin converting enzyme (ACE) and calcium, may be elevated in sarcoidosis patients." (PMID 25580285, 2014). "In some of the patients with sarcoidosis, biochemical markers such as serum ACE, calcium, and 25-hydroxy-vitamin D3 may be elevated in the serum." (PMID 25580285, 2014). "Serum ACE is increased in 30 to 80% of patients with sarcoidosis." (PMID 25110598, 2014). "The levels of serum ACE have been used to monitor progress sarcoidosis in response to therapy." (PMID 24826302, 2013). "BAL lymphocytosis, high CD4/CD8 ratio, and elevated serum ACE levels in this group may be considered as important laboratory markers for the diagnosis of sarcoidosis." (PMID 23521826, 2013). "Normal levels have been found in patients with recently diagnosed sarcoidosis, and elevated levels of ACE may be present in other granulomatous diseases such as tuberculosis, silicosis, leprosy, asbestosis, and granulomatous hepatitis." (PMID 24826302, 2013).